PPP2CA (protein phosphatase 2 catalytic subunit alpha)
Description:
Catalytic subunit of protein phosphatase 2A (PP2A), a serine/threonine phosphatase involved in the regulation of a wide variety of enzymes, signal transduction pathways, and cellular events. PP2A is the major phosphatase for microtubule-associated proteins (MAPs). PP2A can modulate the activity of phosphorylase B kinase casein kinase 2, mitogen-stimulated S6 kinase, and MAP-2 kinase. Cooperates with SGO2 to protect centromeric cohesin from separase-mediated cleavage in oocytes specifically during meiosis I (By similarity). Activates RAF1 by dephosphorylating it at 'Ser-259'. Mediates dephosphorylation of WEE1, preventing its ubiquitin-mediated proteolysis, increasing WEE1 protein levels, and promoting the G2/M checkpoint. Mediates dephosphorylation of MYC; promoting its ubiquitin-mediated proteolysis: interaction with AMBRA1 enhances interaction between PPP2CA and MYC. Mediates dephosphorylation of FOXO3; promoting its stabilization: interaction with AMBRA1 enhances interaction between PPP2CA and FOXO3. Catalyzes dephosphorylation of the pyrin domain of NLRP3, promoting assembly of the NLRP3 inflammasome (By similarity). Together with RACK1 adapter, mediates dephosphorylation of AKT1 at 'Ser-473', preventing AKT1 activation and AKT-mTOR signaling pathway (By similarity). Dephosphorylation of AKT1 is essential for regulatory T-cells (Treg) homeostasis and stability (By similarity). Catalyzes dephosphorylation of PIM3, promoting PIM3 ubiquitination and proteasomal degradation. Part of the striatin-interacting phosphatase and kinase (STRIPAK) complexes. STRIPAK complexes have critical roles in protein (de)phosphorylation and are regulators of multiple signaling pathways including Hippo, MAPK, nuclear receptor and cytoskeleton remodeling. Different types of STRIPAK complexes are involved in a variety of biological processes such as cell growth, differentiation, apoptosis, metabolism and immune regulation. Key mediator of a quality checkpoint during transcription elongation as part of the Integrator-PP2A (INTAC) complex. The INTAC complex drives premature transcription termination of transcripts that are unfavorably configured for transcriptional elongation: within the INTAC complex, PPP2CA catalyzes dephosphorylation of the C-terminal domain (CTD) of Pol II subunit POLR2A/RPB1 and SUPT5H/SPT5, thereby preventing transcriptional elongation.
Synonyms: RP-C; PP2Calpha; PP2AC; HJS3; NEDLBA; PP2CA
Tractability: Small molecule: a drug acting on it is in phase 2 or 3 trials; a structure with a bound ligand is known; a high-quality ligand is known. Antibody: its Gene Ontology location is reachable by antibodies, with medium confidence. PROTAC: UniProt records ubiquitination sites on it; ubiquitination databases record sites on it; its protein half-life has been measured; a small molecule that binds it is known.
Target class: Protein Phosphatase; Phosphatase; Serine/threonine protein phosphatase; Enzyme
Gene: Protein-coding gene on chromosome 5 (134,193,978 to 134,226,083, reverse strand). Ensembl gene ENSG00000113575.
Subcellular location: Cytoplasm; Nucleus; Chromosome; Chromosome, centromere; Cytoplasm, cytoskeleton, spindle pole
Pathways (Reactome):
Signal Transduction: Beta-catenin phosphorylation cascade; DARPP-32 events; Degradation of beta-catenin by the destruction complex; Disassembly of the destruction complex and recruitment of AXIN to the membrane; ERK/MAPK targets; ERKs are inactivated; Negative regulation of MAPK pathway; PI5P, PP2A and IER3 Regulate PI3K/AKT Signaling; RAF activation; RHO GTPases Activate Formins; Spry regulation of FGF signaling
Cell Cycle: Amplification of signal from unattached kinetochores via a MAD2 inhibitory signal; Cyclin A/B1/B2 associated events during G2/M transition; Cyclin D associated events in G1; EML4 and NUDC in mitotic spindle formation; Inhibition of replication initiation of damaged DNA by RB1/E2F1; Initiation of Nuclear Envelope (NE) Reformation; MASTL Facilitates Mitotic Progression; Mitotic Prometaphase; Resolution of Sister Chromatid Cohesion; Separation of Sister Chromatids
Disease: APC truncation mutants have impaired AXIN binding; AXIN missense mutants destabilize the destruction complex; CTNNB1 S33 mutants aren't phosphorylated; CTNNB1 S37 mutants aren't phosphorylated; CTNNB1 S45 mutants aren't phosphorylated; CTNNB1 T41 mutants aren't phosphorylated; Signaling by GSK3beta mutants; Truncations of AMER1 destabilize the destruction complex
Immune System: Co-inhibition by CTLA4; Co-stimulation by CD28; PKR-mediated signaling
Metabolism: PP2A-mediated dephosphorylation of key metabolic factors; Regulation of glycolysis by fructose 2,6-bisphosphate metabolism
Cellular responses to stimuli: Turbulent (oscillatory, disturbed) flow shear stress activates signaling by PIEZO1 and integrins in endothelial cells
Hemostasis: Platelet sensitization by LDL
Metabolism of RNA: Nonsense Mediated Decay (NMD) enhanced by the Exon Junction Complex (EJC)
Gene Ontology:
Molecular function: phosphoprotein phosphatase activity; protein binding; protein heterodimerization activity; protein serine/threonine phosphatase activity; protein tyrosine phosphatase activity; RNA polymerase II CTD heptapeptide repeat S2 phosphatase activity; RNA polymerase II CTD heptapeptide repeat S5 phosphatase activity; RNA polymerase II CTD heptapeptide repeat S7 phosphatase activity; tau protein binding; GABA receptor binding; hydrolase activity
Biological process: negative regulation of canonical Wnt signaling pathway; negative regulation of epithelial to mesenchymal transition; negative regulation of hippo signaling; negative regulation of phosphatidylinositol 3-kinase/protein kinase B signal transduction; protein dephosphorylation; regulation of G1/S transition of mitotic cell cycle; regulation of transcription elongation by RNA polymerase II; RNA polymerase II transcription initiation surveillance; intracellular signal transduction; mitotic cell cycle; positive regulation of NLRP3 inflammasome complex assembly; regulation of cell differentiation; regulation of growth; regulation of hippo signaling; regulation of microtubule polymerization; response to lead ion; snRNA processing; T cell homeostasis; vascular endothelial cell response to oscillatory fluid shear stress; negative regulation of glycolytic process through fructose-6-phosphate; regulation of transcription by RNA polymerase II
Cellular component: chromatin; chromosome; cytoplasm; cytosol; extracellular exosome; FAR/SIN/STRIPAK complex; INTAC complex; integrator complex; membrane raft; nucleus; protein phosphatase type 2A complex; protein serine/threonine phosphatase complex; membrane; microtubule cytoskeleton; mitochondrion; chromosome, centromeric region; plasma membrane; spindle pole; synapse
Genetic constraint (gnomAD): Loss-of-function variants: 5 observed, 33.36 expected, observed/expected ratio (o/e) 0.15, 90% interval 0.077 to 0.31. The upper end of that interval is the gene's LOEUF score, 0.31, which puts it in group 1 of 6, group 1 being the genes least tolerant of losing a copy. Missense variants: 85 observed, 383.63 expected, observed/expected ratio (o/e) 0.22, 90% interval 0.19 to 0.26. Synonymous variants: 147 observed, 131.64 expected, observed/expected ratio (o/e) 1.12, 90% interval 0.98 to 1.28.
Gene-disease validity (ClinGen):
ClinGen rates the evidence that PPP2CA causes each of these diseases.
complex neurodevelopmental disorder (autosomal dominant): Definitive. A disorder that involves more than one phenotype associated with the central nervous system, including but not limited to intellectual disability, autism, and seizures (epilepsy).
Homologues: Orthologues: chimpanzee PPP2CA (100% identical), guinea pig PPP2CA (100% identical), pig PPP2CA (100% identical), rabbit PPP2CA (100% identical), mouse Ppp2ca (99% identical), dog PPP2CA (99% identical), rat Ppp2cal1 (99% identical), tropical clawed frog ppp2ca (99% identical), zebrafish ppp2cab (97% identical), Drosophila melanogaster mts (94% identical), macaque SKP1 (93% identical), Caenorhabditis elegans let-92 (89% identical). Paralogues in human: PPP2CB (97% identical), PPP4C (66% identical), PPP6C (58% identical), PPP1CB (47% identical), PPP1CA (47% identical), PPP1CC (47% identical), PPP3CA (41% identical), PPP3CB (40% identical), PPP3CC (40% identical), PPP5C (35% identical), PPEF2 (35% identical), PPEF1 (34% identical).
Diseases named in the same sentence as PPP2CA in open-access papers:
PPP2CA is named in the same sentence as 101 diseases in open-access papers, as found by Europe PMC text mining. Sharing a sentence is not in itself a finding about the gene and the disease. The quoted sentences say what the papers report.
breast carcinoma (16 papers, 2013 to 2025). "Disease associations of the identified putative PPP2CA substrates showed involvement in micrognathism, developmental delay, microcephaly, mental retardation, congenital epicanthus, breast cancer, and neurodevelopmental disorders." (PMID 38450154, 2024). "In this study, we scanned for mutations in the PP2A catalytic subunit, PPP2CA transcript (mRNA) in various breast cancer cell lines." (PMID 24460909, 2014). "We observed a significant association of putative PPP2CA substrates with breast cancer as well as numerous developmental disorders, such as micrognathism, developmental delay, microcephaly, mental retardation, congenital epicanthus, and neurodevelopmental disorders." (PMID 38450154, 2024). "Taken together, the results implicated that PPP2CA may affect breast cancer cell migration through interacting with PKCζ." (PMID 29491746, 2018). "Ubiquitination of PPP2CA, the catalytic subunit of PP2A, has been implicated in breast cancer growth 48, in contrast, PPP2CA gene is highly expressed in hepatocellular carcinoma tissues and its over-expression correlates with poor prognosis." (PMID 40959281, 2025). "Breast cancer cells can downregulate the expression of protein phosphatase 2 catalytic subunit alpha (PPP2CA) in TAMs by delivering miR-183-5p via exosomes to TAMs." (PMID 36624542, 2023). "PPP2CA has been found to promote the proliferation and invasion of breast cancer cells." (PMID 38418940, 2024). "This is mainly because miR-183-5p, which inhibits the expression of PPP2CA, can be transferred from breast cancer cells to macrophages through exosomes, thus, promoting the secretion of proinflammatory cytokines and contributing to tumor progression in breast cancer." (PMID 34829498, 2021). "Co-IP and Western blotting showed that PPP2CA could indeed bind to PKCζ in two types of human breast cancer cell line, including MDA-MB-231 and MCF-7." (PMID 29491746, 2018). "In this study, no mutations were identified in the PPP2CA coding sequence in various breast cancer cell lines." (PMID 24460909, 2014). "Similar, PPP2CA is a vital constituent of PP2A and its downregulation by breast cancer cell-derived exosomes activated NFκB signaling pathway in tumor-associated macrophages." (PMID 36311795, 2022). "With these results, we suggest for the first time that the DEGs of the PPPCs family, except for PPP2CA and PPEF1, lead to reduced infiltration of immune cells in breast cancer tissues, which can affect the development and immunotherapy of breast cancer." (PMID 34964699, 2022). "Of note, only the MDA-MB-231 breast cancer cell line showed a dependency on KRAS, CALM3 as well as PPP2CA." (PMID 35617282, 2022). "Among the highly expressed genes in breast cancer tissues, PPP1CA was negatively correlated with CD8 + T cell and macrophage infiltration, while PPP2CA was positively correlated with infiltration." (PMID 34964699, 2022). "In the Oncomine database, when compared with normal breast tissues, PPP1CA, PPP2CA, PPP4C and PPEF1 were significantly elevated in breast cancer tissues, while PPP1CB, PPP2CB, PPP3CA, PPP3CB, PPP3CC and PPP6C were significantly decreased in breast cancer tissues." (PMID 34964699, 2022). "Screening of PPP2CA coding sequence for mutations, using HRM analysis, could not detect mutations in the adherent human breast cancer cell lines and in an additional panel of 25 tumour cell lines (14 haematological and 11 solid tumour cell lines)." (PMID 24460909, 2014).
hepatocellular carcinoma (8 papers, 2016 to 2025). A malignant tumor that arises from hepatocytes. "BTBD10 functions as an activator of AKT family members by inhibiting PPP2CA-mediated dephosphorylation, and a few studies have identified it as a prognostic risk factor in hepatocellular carcinoma and glioma." (PMID 37007130, 2023).
prostate carcinoma (8 papers, 2017 to 2025). A carcinoma that arises from epithelial cells of the prostate gland. "More importantly, the loss of PPP2CA promotes prostate cancer’s invasiveness due to the activation of AKT/β-catenin signaling pathways and induced EMT." (PMID 34217266, 2021). "In prostate cancer, PPP2CA downregulation is linked to castration resistance and the activation of epithelial-mesenchymal transition (EMT), contributing to a more invasive tumor phenotype, restoration of PPP2CA activity can reverse EMT, significantly suppressing tumor growth and metastasis." (PMID 40770810, 2025). "PPP2CA mutation and deep deletion events occur in 0.4–1.4% of patients with prostate cancer, further highlighting the diversity of genetic aberrations in AKT regulators that could promote oncogenic PI3K signaling." (PMID 32630372, 2020). "Combined with the upregulation of PPP2CA expression, it will inhibit the malignant phenotype of malignant tumor cells such as colon cancer, thyroid cancer, and prostate cancer." (PMID 34485508, 2021). "PPP2CA has also been identified as the p70S6K phosphatase in both human prostate carcinoma cell line DU-145 and human hepatic cancer cell line HepG2." (PMID 32316234, 2020). "In addition, genetic alterations in PPP2CA (protein phosphatase 2 catalytic subunit alpha) that encodes the negative AKT regulator PP2A have also been observed in prostate cancer, and PP2A loss has been linked to prostate cancer progression and metastatic potential in the clinic." (PMID 32630372, 2020). "PPP2CA could reverse EMT and suppress prostate cancer growth and metastasis." (PMID 28107197, 2017).
viral infection (6 papers, 2018 to 2023). "We have presented evidence of a negative regulation of PPP2CA that was transduced by transfection or by viral infection." (PMID 30050113, 2018). "Moreover, several novel genes score in the top 20 for multiple strains, including UBE2M, MBNL1, FBXW7, PCGF1, and PPP2CA, implicating those gene products in processes important for viral infection across HIV-1 strains." (PMID 36744886, 2023).
Alzheimer disease (5 papers, 2011 to 2024). A progressive, neurodegenerative disease characterized by loss of function and death of nerve cells in several areas of the brain leading to loss of cognitive function such as memory and language. "Besides, Ppp2ca is also known to be associated with tauopathies, such as Alzheimer’s disease and others." (PMID 27213341, 2016). "As for PPP2CA, it is in association with neurodevelopmental disorder and language delay with or without structural brain abnormalities and Alzheimer's disease." (PMID 35075370, 2022).
developmental delay (5 papers, 2018 to 2026). "Previous clinical observations have linked mutations in PPP2CA to intellectual disability, developmental delay, ataxia, and structural brain abnormalities, suggesting a potential role for PP2Acα in cerebellar pathophysiology." (PMID 41509924, 2026). "Previously, de novo mutations in PPP2CA and another PP2A subunit, PPP2R5D, have been identified in patients with intellectual disability and developmental delay." (PMID 38450154, 2024).
epilepsy (5 papers, 2011 to 2025). A brain disorder characterized by episodes of abnormally increased neuronal discharge resulting in transient episodes of sensory or motor neurological dysfunction, or psychic dysfunction. "In subsequent genes, SLC2A1 and PPP2CA, related to ID and epilepsy, we found another de novo, pathogenic variants." (PMID 36674629, 2023). "In PPP2CA, the gene related to neurodevelopmental disorder, we identified known missense variant c.794A>G in Patient 21, who was diagnosed with epilepsy, developmental regression, and speech disorder." (PMID 36674629, 2023). "The brown module has 53 hub genes, including genes associated with dopaminergic signaling (GNB1, GSK3B), long-term potentiation (PPP1CB), opioid signaling (PPP2CA, PPP3CA, PPP3R1), epilepsy (SYN1), and Parkinson’s disease (SNCA)." (PMID 28710498, 2017).
ovarian carcinoma (5 papers, 2016 to 2025). A malignant neoplasm originating from the surface ovarian epithelium. "This study explores PPP2CA dysregulation in ovarian cancer (OC) progression via lactate production and evaluates Triptolide’s potential to regulate this process." (PMID 40770810, 2025). "Luteolin can be used to treat prostate cancer (JPRN-jRCTs041230029), and inhibit ovarian cancer stem cells proliferation by interfering with the KDM4C/PPP2CA/YAP pathway (ChiCTR2200056567)." (PMID 40620671, 2025).
colon cancer (4 papers, 2020 to 2024). "PPP2CA is a direct target of miR‐155, and its overexpression leads to PPP2CA low levels in colon cancer." (PMID 35087589, 2022). "The results implicated protein phosphatase 2 catalytic subunit alpha (PPP2CA) in the occurrence and development of colon cancer, and its potential to serve as a therapeutic target in colon cancer." (PMID 32582275, 2020).